RABL2B (RAB, member of RAS oncogene family like 2B)
Description:
Small GTPase required for ciliation. Activated in a guanine nucleotide exchange factor (GEF)-independent manner via its intrinsic GDP for GTP nucleotide exchange ability. Involved in ciliary assembly by binding the intraflagellar transport (IFT) complex B from the large pool pre-docked at the base of the cilium and thus triggers its entry into the cilia.
Tractability: PROTAC: ubiquitination databases record sites on it.
Gene: Protein-coding gene on chromosome 22 (50,767,491 to 50,783,760, reverse strand). Ensembl gene ENSG00000079974.
Subcellular location: Cytoplasm, cytoskeleton, microtubule organizing center, centrosome, centriole; Cytoplasm, cytoskeleton, cilium basal body; Cytoplasm
Subcellular location (Human Protein Atlas): Basal body; Centrosome; Vesicles
Gene Ontology:
Molecular function: G protein activity; protein binding; GTPase activity; GTP binding
Biological process: cilium assembly; intraciliary transport; microtubule-based movement
Cellular component: centriole; centrosome; ciliary basal body; cytoplasm; pericentriolar material; cilium
Genetic constraint (gnomAD): Loss-of-function variants: 15 observed, 21.1 expected, observed/expected ratio (o/e) 0.71, 90% interval 0.47 to 1.09. The upper end of that interval is the gene's LOEUF score, 1.09, which puts it in group 4 of 6, group 1 being the genes least tolerant of losing a copy. Missense variants: 158 observed, 203.8 expected, observed/expected ratio (o/e) 0.78, 90% interval 0.68 to 0.88. Synonymous variants: 61 observed, 77.69 expected, observed/expected ratio (o/e) 0.79, 90% interval 0.64 to 0.97.
Homologues: Orthologues: chimpanzee RABL2A (97% identical), macaque RABL2B (96% identical), dog RABL2B (86% identical), rat Rabl2 (83% identical), mouse Rabl2 (81% identical), tropical clawed frog rabl2b (73% identical), zebrafish rabl2 (70% identical), chimpanzee RABL2B (60% identical). Paralogues in human: RABL2A (99% identical), RAB24 (24% identical), RAB36 (24% identical), RAB14 (24% identical), RAB33A (24% identical), RAB5C (24% identical), RAB11A (24% identical), RAB11B (24% identical), RAB12 (24% identical), RAB18 (24% identical), RAB34 (24% identical), RAB5A (24% identical), and 56 more.
Diseases named in the same sentence as RABL2B in open-access papers:
RABL2B is named in the same sentence as 7 diseases in open-access papers, as found by Europe PMC text mining. Sharing a sentence is not in itself a finding about the gene and the disease. The quoted sentences say what the papers report.
autism spectrum disorder (1 paper, 2025). A spectrum of developmental disorders that includes autism, and Asperger syndrome. "We also found an RABL2B deletion classically associated with Phelan–McDermid syndrome (PHMDS), which is linked to global developmental delay, cognitive deficits, and autism spectrum disorder-like behavioral patterns." (PMID 40869914, 2025).
lung carcinoma (1 paper, 2023). "Both RABL2B and circRABL2B are derived from RABL2B pre-mRNA, and RABL2B mRNA was also significantly downregulated in the lung cancer tissues in comparison with the normal tissues, being similar to the TCGA data." (PMID 37324942, 2023). "Meanwhile, knock-down of RABL2B did not affect proliferation, cloning formation, migration and invasion of lung cancer cells." (PMID 37324942, 2023).
RABL2B also shares sentences with these, for which no sentence is quoted: cancer (1 paper); cognitive deficits (1); developmental delay (1); infection (1); Phelan-McDermid syndrome (1).